COL21A1 (collagen type XXI alpha 1 chain)
Synonyms: FP633; COLA1L
Tractability: Antibody: UniProt places it where antibodies can reach, with high confidence; its Gene Ontology location is reachable by antibodies, with high confidence; UniProt predicts a signal peptide or a membrane-spanning region.
Gene: Protein-coding gene on chromosome 6 (56,056,590 to 56,394,094, reverse strand). Ensembl gene ENSG00000124749.
Subcellular location: Secreted, extracellular space, extracellular matrix; Cytoplasm
Subcellular location (Human Protein Atlas): Cytosol; Predicted to be secreted
Pathways (Reactome):
Extracellular matrix organization: Collagen biosynthesis and modifying enzymes; Collagen chain trimerization
Gene Ontology:
Molecular function: extracellular matrix structural constituent conferring tensile strength
Cellular component: cytosol; extracellular matrix; collagen type XXI trimer; endoplasmic reticulum lumen; extracellular region; cytoplasm
Genetic constraint (gnomAD): Loss-of-function variants: 83 observed, 74.4 expected, observed/expected ratio (o/e) 1.12, 90% interval 0.93 to 1.34. The upper end of that interval is the gene's LOEUF score, 1.34, which puts it in group 5 of 6, group 1 being the genes least tolerant of losing a copy. Missense variants: 864 observed, 832.75 expected, observed/expected ratio (o/e) 1.04, 90% interval 0.98 to 1.1. Synonymous variants: 346 observed, 297.82 expected, observed/expected ratio (o/e) 1.16, 90% interval 1.06 to 1.27.
Homologues: Orthologues: macaque COL21A1 (98% identical), dog COL21A1 (92% identical), pig COL21A1 (92% identical), rabbit COL21A1 (91% identical), guinea pig COL21A1 (87% identical). Paralogues in human: COL4A4 (28% identical), COL4A5 (26% identical), COL4A1 (25% identical), COL4A2 (24% identical), COL4A6 (24% identical), COL5A1 (24% identical), COL11A1 (24% identical), COL1A1 (24% identical), COL2A1 (23% identical), COL4A3 (23% identical), COL5A2 (23% identical), COL11A2 (23% identical), and 25 more.
Diseases named in the same sentence as COL21A1 in open-access papers:
COL21A1 is named in the same sentence as 21 diseases in open-access papers, as found by Europe PMC text mining. Sharing a sentence is not in itself a finding about the gene and the disease. The quoted sentences say what the papers report.
cleft lip (3 papers, 2019 to 2023). Congenital defect in the upper lip where the maxillary prominence fails to merge with the merged medial nasal prominences. "The role of COL21A1 is also not understood, but human GWAS studies on atypical psychosis and nonsyndromic cleft lip/palate implicate a role of COL21A1." (PMID 33669899, 2021).
Hypertension (2 papers, 2020 to 2023). The presence of chronic increased pressure in the systemic arterial system. "Another study aimed at finding rare and common variants associated with hypertension identified 31 novel genetic regions—rare missense variants in RBM47, COL21A1, and RRAS." (PMID 36902588, 2023). "They identified 30 new blood pressure- or hypertension-associated genetic regions in the general population, including 3 rare missense variants in RBM47, COL21A1 and RRAS with larger effects than common variants." (PMID 33240327, 2020).
Alzheimer disease (1 paper, 2022). A progressive, neurodegenerative disease characterized by loss of function and death of nerve cells in several areas of the brain leading to loss of cognitive function such as memory and language. "We also found that rs17823624 was eQTL of DST (Dystonine), a gene close to COL21A1, for which variants were found to be associated with lung function and Alzheimer’s disease." (PMID 35624665, 2022).
dilated cardiomyopathy (1 paper, 2016). Cardiomyopathy which is characterized by dilation and contractile dysfunction of the left and right ventricles. "Upregulated COL4A5, COL9A1, COL21A1, and COL23A1 genes, encode collagens that have not previously been reported to be related to dilated cardiomyopathy." (PMID 27936202, 2016).
gastric carcinoma (1 paper, 2024). A carcinoma that arises from epithelial cells of the stomach. "Another study focused on identifying hub genes and pathways in gastric carcinoma development, found that type XXI collagen alpha chain 1 (Col21a1) might have a direct role in the enrichment of some pathways involved in tumorigenesis, such as DNA repair and KRAS signaling pathway." (PMID 39769286, 2024).
mucinous ovarian cancer (1 paper, 2018). An invasive malignant neoplasm that arises from the ovary and is characterized by the presence of malignant epithelial cells that contain intracytoplasmic mucin and may resemble the epithelial cells of the endocervix or gastrointestinal tract. "The immunohistochemical analysis of LOX, COL1A2, COL3A1, COL21A1, and ALDH1A1 was performed for few cases of endometrioid, serous, and mucinous ovarian cancer in order to verify the localization of analyzed proteins in the real cancer tissue." (PMID 30583585, 2018).
orofacial cleft (1 paper, 2019). A disorder of facial skeleton that is characterized by cleft lip and/or cleft palate that result in feeding, speech and hearing problems caused by failures during development. "As this gene has never been discussed or claimed to have a role in clefting, our finding is the first report of COL21A1 at 6p12.2 region that might be associated with nonsyndromic orofacial cleft." (PMID 30924295, 2019). "This novel finding would help to shed light on the regulation of COL21A1 on the orofacial cleft formation." (PMID 30924295, 2019). "No one has reported the role of COL21A1 in association with nonsyndromic orofacial cleft so far but the mutation at the 6p region has been attained before." (PMID 30924295, 2019).
ovarian carcinoma (1 paper, 2018). A malignant neoplasm originating from the surface ovarian epithelium. "Moreover, this is also for the first time when expression of COL21A1 was noted not only in ovarian cancer but also in any other cancers." (PMID 30583585, 2018). "However, the most abundantly expressed type of collagen in the investigated ovarian cancer samples was COL21A1, which is responsible for three-dimensional structure of dense connective tissue." (PMID 30583585, 2018). "The immunohistochemical analysis of COL1A2, COL3A1, and COL21A1 revealed that regardless of the type of analyzed ovarian cancer subtype the expression of those proteins was present not only in the ECM surrounding the tumor (what was expected) but also in cancer cells." (PMID 30583585, 2018).
Parkinson disease (1 paper, 2017). A progressive degenerative disorder of the central nervous system characterized by loss of dopamine producing neurons in the substantia nigra and the presence of Lewy bodies in the substantia nigra and locus coeruleus. "In addition, four genes associated with neurological disorders were significantly upregulated in hydrogel-cultured cells (NR4A2, Parkinson’s disease; A2M & HMOX1, Alzheimer’s; COL21A1, atypical psychosis)." (PMID 28097054, 2017).
small cell lung carcinoma (1 paper, 2022). Small cell lung cancer (SCLC) is a highly aggressive malignant neoplasm, accounting for 10-15% of lung cancer cases, characterized byrapid growth, and early metastasis. "In previous GWAS, COL21A1 showed associations with lung function and to a lesser extend with allergic sensitisation and small cell lung carcinoma." (PMID 35624665, 2022).
tumor (7 papers, 2010 to 2023). "In particular, COL21A1, which we observed to be down-regulated and potentially controlled by miR-155 is known to be important for cell plasticity and extracellular matrix remodeling and has been reported to be involved in tumor cell invasion and metastasis." (PMID 23723971, 2013). "For instance, COL8A1, COL8A2, and COL21A1 were only detected in normal tissues whereas COL7A1 and MUC1 were exclusively identified in tumor samples." (PMID 34199725, 2021).
cancer (2 papers, 2018 to 2022). A tumor composed of atypical neoplastic, often pleomorphic cells that invade other tissues. "However, some cells presented stronger COL21A1 expression then other ones in all types of carcinomas (red arrows)." (PMID 30583585, 2018).
COL21A1 also shares sentences with these, for which no sentence is quoted: Autoimmunity (1 paper); cardiac hypertrophy (1); cardiomyopathy (1); Cirrhosis (1); gastric tumors (1); Hepatic fibrosis (1); neurological disorders (1); psychosis (1); renal fibrosis (1).